VAT1L (vesicle amine transport 1 like)
Description:
Putative NADPH-dependent quinone oxidoreductase.
Synonyms: KIAA1576
Tractability: Small molecule: it has a binding pocket of medium quality. PROTAC: ubiquitination databases record sites on it; its protein half-life has been measured.
Gene: Protein-coding gene on chromosome 16 (77,788,564 to 77,980,107, forward strand). Ensembl gene ENSG00000171724.
Subcellular location (Human Protein Atlas): Cytosol
Gene Ontology:
Molecular function: protein binding; NADPH dehydrogenase (quinone) activity; quinone reductase (NADPH) activity; oxidoreductase activity; zinc ion binding
Genetic constraint (gnomAD): Loss-of-function variants: 34 observed, 42.68 expected, observed/expected ratio (o/e) 0.8, 90% interval 0.61 to 1.06. The synonymous counts are far from expectation, so gnomAD's model fits this gene poorly and the ratio says little. Missense variants: 615 observed, 534.39 expected, observed/expected ratio (o/e) 1.15, 90% interval 1.08 to 1.23. Synonymous variants: 253 observed, 202.23 expected, observed/expected ratio (o/e) 1.25, 90% interval 1.13 to 1.39.
Homologues: Orthologues: macaque VAT1L (99% identical), mouse Vat1l (98% identical), rat Vat1l (98% identical), guinea pig VAT1L (97% identical), dog VAT1L (97% identical), chimpanzee VAT1L (93% identical), rabbit VAT1L (89% identical), pig VAT1L (87% identical), tropical clawed frog vat1l (87% identical), zebrafish vat1l (82% identical), Caenorhabditis elegans D2063.1 (18% identical), Caenorhabditis elegans ZK829.7 (17% identical), and 3 more. Paralogues in human: VAT1 (40% identical), CRYZ (24% identical), PTGR3 (23% identical), TP53I3 (23% identical), RTN4IP1 (20% identical), MECR (19% identical), SORD (17% identical), ADH5 (17% identical), ADH4 (17% identical), CRYZL1 (16% identical), ADH1A (16% identical), ADH1C (16% identical), and 5 more.
Diseases named in the same sentence as VAT1L in open-access papers:
VAT1L is named in the same sentence as 10 diseases in open-access papers, as found by Europe PMC text mining. Sharing a sentence is not in itself a finding about the gene and the disease. The quoted sentences say what the papers report.
schizophrenia (5 papers, 2015 to 2025). A major psychotic disorder characterized by abnormalities in the perception or expression of reality. "The synaptic vesicle membrane protein VAT‐1 homolog‐like (VAT1L) has been associated with schizophrenia and VAT1, its paralog, is responsible for the storage and release of neurotransmitters in synapses and its activity in keratinocytes is calcium‐dependent." (PMID 39910963, 2025). "The VAT1L gene has been associated with schizophrenia in some GWASs and subsequent pathway enrichment analysis suggested its involvement in neural and immune system-related pathways." (PMID 33562295, 2021).
cognitive decline (2 papers, 2017 to 2025). "A previous study involving the ADNI cohort identified an intronic SNP in VAT1L in association with cognitive decline measured by ADAS-cog." (PMID 40725474, 2025). "Additionally, a genome-wide association study of the rate of cognitive decline in Alzheimer's disease indicated that rs9934540 genetic variants in the VAT1L gene intron were positively associated with the development of Alzheimer's disease." (PMID 28415562, 2017).
calcific aortic valve disease (1 paper, 2021). "Likewise, the VAT1L gene has been associated with the von Economo neurons in brain functional analyses and in calcific aortic valve disease, among other diseases." (PMID 33562295, 2021).
essential thrombocythemia (1 paper, 2017). A chronic myeloproliferative neoplasm that involves primarily the megakaryocytic lineage. "VAT1L is mainly expressed in the brain and CALR mutation status defined subtypes of essential thrombocythemia with substantially different clinical course and outcomes, thus it could be a potential biomarker for myeloproliterative neoplasm." (PMID 29069830, 2017).
Obesity (1 paper, 2024). Accumulation of substantial excess body fat. "Vesicle amine transport 1 like (VAT1L) is a protein that is predicted to enable oxidoreductase activity and zinc ion-binding activity, and it is a candidate gene identified in obesity and thermogenesis." (PMID 39130751, 2024).
VAT1L also shares sentences with these, for which no sentence is quoted: Alzheimer disease (1 paper); breast carcinoma (1); cancer (1); spinocerebellar ataxia (1); tendinopathy (1).